KRAS (KRas proto-oncogene, GTPase)
Diseases named in the same sentence as KRAS in open-access papers (continued):
Sharing a sentence is not in itself a finding about the gene and the disease.
lung cancer (continued). "The Zinc-finger E-box-binding Homeobox-1 (ZEB1) is a transcription factor that promotes epithelial–mesenchymal transition (EMT) and acts as an oncogene in KRAS-mutated lung cancer models." (PMID 27456471, 2016). "A phase II trial in KRAS mutated lung cancer patients compared docetaxel alone to docetaxel with selumetinib (an anti-MEK1/MEK2)." (PMID 27433281, 2016). "Previous studies demonstrated that lung cancer with a KRAS mutation showed increased numbers of neutrophils through the expression of CXCL-1 and CXCL-2." (PMID 27483433, 2016). "Since KRAS mutations were frequently evaluated alongside EGFR in cases of lung cancers at our institution, we also wanted to compare the performance of both methods on this gene." (PMID 27043212, 2016). "KRAS mutation is detected at high rate in lung cancer, colorectal cancer (CRC), and pancreatic cancer." (PMID 27517148, 2016). "A SNP in the let-7 miRNA binding site in the 3′UTR of KRAS is associated with risk of lung cancer development and HIF1A c.*191T>C SNP in the 3′ UTR of the gene is significantly correlated with rectal cancer risk." (PMID 26872370, 2016). "The TTF1+ xMD procured lung carcinoma cells demonstrated a 5-8-fold increase in KRAS mutation percentage in comparison to the whole cytospin macrodissection (46–76% vs. 9%)." (PMID 26999048, 2016). "KRAS mutations are present in many different tumors, including carcinomas of the lung, as KRAS is one of the most commonly mutated genes in human cancer." (PMID 27655296, 2016). "Conversely, ectopic expression of iNOS was shown to increase the tumor growth of the KRAS mutation-positive Calu-6 human lung carcinoma cell line." (PMID 27285753, 2016). "In summary, presented data introduce KRAS/PAK1/Crk axis as one of the prominent signaling pathways downstream of mutated KRAS in lung cancer." (PMID 25956913, 2015). "To conclude, in this study we report the frequency of EGFR mutations in a cohort of 956 lung cancer patients as well as the frequency of alterations in KRAS, BRAF, MET, PIK3CA and ALK genes in a subset of these patients." (PMID 26208325, 2015). "Approximately 25% of lung adenocarcinomas, a dominant form of lung cancer harbor oncogenic KRAS mutations, and this poses a significant therapeutic challenge, as KRAS mutations are generally associated with poor prognosis and resistance to chemotherapy." (PMID 25897662, 2015). "We also demonstrated that LAPTM4B promoted survival and autophagy as well as activated the NRF2 stress response pathway in lung cancer cells, particularly those with mutations in the KRAS oncogene, under serum deprived conditions." (PMID 26343532, 2015). "Transcription enhancer factor (TEF-1) is known to be upregulated in tumors from a KRAS mutated, genetically engineered mouse model of lung cancer." (PMID 26028668, 2015). "KRAS is a frequently mutated oncogene in lung cancer and among the most refractory to EGFR targeted therapy." (PMID 25992771, 2015). "EGFR and KRAS mutations, activation of Src kinase, and elevated expression of interleukin-6 (IL-6) are among several molecular aberrations have been identified in lung cancer that often result in the activation of STAT3." (PMID 26314961, 2015). "This variant, the let-7 complementary site (LCS6) in the KRAS 3′-UTR, is associated with KRAS gene upregulation and let-7 lower levels; however this polymorphism correlates with a modest increase in lung cancer risk." (PMID 26583084, 2015). "In a type of lung cancer called adenocarcinoma, the KRAS gene is mutated in about one-third of tumors and the EGFR gene is mutated in about 15%." (PMID 26047463, 2015).
lung cancer (continued). "At present, there is little information regarding Polβ expression in KRAS mutated lung cancer, so that this biomarker will have to be assessed in this type of cancer in the future." (PMID 26353932, 2015). "A point-mutation in codon 12 of KRAS was evaluated with RAS-specific DNA sequencing, which confirmed that the presence of a KRAS point-mutation in lung cancer indicated a poor prognosis and shorter DFS." (PMID 25908947, 2015). "Studies suggest that KRAS mutations play significant roles in the initiation and progression of lung cancer and contribute to the poor prognosis of the disease." (PMID 26452035, 2015). "We therefore examined the collective contribution of EGFR, HER2 and HER3 in the molecular mechanism underlying the pathogenesis of KRAS mutant lung cancer." (PMID 25992771, 2015). "KRAS mutations in lung cancer occur primarily at codon 12 or 13, making the protein GAP insensitive and constitutively GTP bound leading to the activation of downstream effectors." (PMID 26668062, 2015). "The mutated genes are often involved in controlling the growth of cells, such as two genes called EGFR and KRAS, which are associated with forms of lung cancer." (PMID 26047463, 2015). "In particular the KRAS(G12C) mutation, the most abundant in lung cancer, associates with a weaker response to cisplatin treatment compared to wt and other tested mutations." (PMID 26353932, 2015). "The Biomarker-integrated Approaches of Targeted Therapy for Lung Cancer Elimination 1 (BATTLE1) study depicted sorafenib as a successful drug in patients with KRAS mutated tumors, an effect that was largely attributed to RAF inhibition." (PMID 25563357, 2014). "KRAS mutations and amplifications are largely mutually exclusive in uterine, gastric, and lung cancers." (PMID 24874471, 2014). "Given the emerging role of KRAS mutations in lung cancer oncogenesis and progression, the chance of silencing this oncogene is of vital interest." (PMID 25593996, 2014). "For example, KRAS is strongly associated with pancreatic, colorectal and lung cancers, whereas NRAS is the isoform most frequently mutated in haemopoietic tumours." (PMID 25109951, 2014). "This is the case for the 20-50% of lung cancer patients that harbor activating point mutations in the KRAS GTPase gene." (PMID 24955217, 2014). "In our sample set 6.3% of KRAS-associated lung cancers metastasized to local regions, 9.1% to lymphs and 5.1% of cancers metastasized to distant organs in our sample set." (PMID 24760004, 2014). "For example, the G12C mutation observed in KRAS in lung cancers is associated with exposure to tobacco smoke mutagens." (PMID 25109951, 2014). "It is possible that the DDR2 gene mutation was detected in squamous cell component of lung cancer and KRAS gene mutation was detected in adenocarcinoma component of this malignancy." (PMID 25173530, 2014). "The overall metabolic deregulation driven by KRAS mutations in lung cancer and systematic characterization of the metabolic pathways active in lung cancer cells harboring different KRAS mutations are therefore still not clear." (PMID 24952473, 2014). "7.7% of KRAS-associated lung cancers were adenocarcinomas and 6.1% of KRAS mutations associated with ‘low differentiation’ cancers and 7.4% of KRAS mutations were ‘mid differentiation’ cancers." (PMID 24760004, 2014). "Although KRAS mutations represent a prognostic factor for colorectal and lung cancer, their correlation with the biological behaviour of gastric tumours is still poorly defined." (PMID 24454858, 2014).
lung cancer (continued). "In EGFR mutant or KRAS mutant lung cancer models, tumor regression associated with apoptosis was also observed only when the PI3K/AKT pathway and MEK/MAPK pathway were simultaneously blocked." (PMID 24337632, 2014). "Loss of p62, not only reduces tumor formation in a KRAS-induced lung cancer mouse model, but has also been implicated in sustaining NF-κB activity induced by KRAS-IL1α in pancreatic cancer." (PMID 24955217, 2014). "In a study of pleomorphic carcinomas of the lung, one out of six cases had a KRAS mutation detected only in the adenocarcinoma component." (PMID 24742923, 2014). "We suggest the introduction of EGFR and KRAS mutation status analysis in the purpose of personalized lung carcinoma therapy of ILADC." (PMID 24782938, 2014). "The presence of an EML4-ALK translocation with concomitant EGFR/KRAS mutations is very rare among lung cancer patients." (PMID 23341890, 2013). "The serine/threonine kinase, LKB1, is a tumor suppressor that has been found mutated in lung cancer concurrently with KRAS mutations." (PMID 23825589, 2013). "Since KRAS mutation was first found in human lung cancer in 1984, much effort has been expended to evaluate its clinical implication." (PMID 23724098, 2013). "LKB1 loss has been observed concurrently with KRAS oncogenic mutations in human lung cancer, and animal models have confirmed the synergy of the combined mutations." (PMID 23825589, 2013). "For anti-EGFR therapy prediction, we demonstrate reliable in situ detection of KRAS mutations in codon 12 and 13 in colon and lung cancers in three different types of routinely processed tissue materials." (PMID 24280411, 2013). "iMDK inhibited the cell growth of MDK-positive H441 lung adenocarcinoma cells that harbor an oncogenic KRAS mutation and H520 squamous cell lung cancer cells, both of which are types of untreatable lung cancer." (PMID 23976985, 2013). "A recent randomized trial demonstrated that the combination of bexarotene (the first RXR-selective retinoid) with/tivantinib (a MET inhibitor) and erlotinib is effective as a treatment for KRAS-mutation-driven lung cancer and is well-tolerated." (PMID 23520448, 2013). "These mice were crossed into a newly generated Cre-recombinase inducible KRAS-driven murine lung cancer model to examine the effect of keratin loss on morphology, invasion and metastasis as well as expression of EMT related genes in the resulting tumors." (PMID 23536778, 2013). "In particular, KRAS mutations are among the most common genetic abnormalities in several types of human cancer, including pancreatic cancer, colon cancer, and lung cancer." (PMID 22463874, 2012). "The observed KRAS mutation frequency is close to the 39 % reported in a Dutch validation study for HRM that analyzed a small group of lung cancer patients." (PMID 22528563, 2012). "This includes not only adenocarcinoma, in which KRAS mutation is commonly observed, but also other major lung cancer histologies including squamous cell carcinoma, in which KRAS mutation is rare." (PMID 22654667, 2012). "The RAS oncogene is mutated in up to ∼30% of lung cancers, with the majority of mutations found in the KRAS gene." (PMID 22438909, 2012). "Although KRAS is frequently mutated in human cancers including pancreatic, colorectal and lung cancers, KRAS mutations are extremely rare in breast cancer." (PMID 22701724, 2012). "KRAS was initially identified in a human lung cancer cell in 1982 and, since then has been shown to be mutated in 35%–50% of all non-small cell lung cancers." (PMID 23202889, 2012). "The majority of human lung cancers are adenocarcinomas carrying somatic mutations in the genes that encode the EGFR/KRAS/BRAF pathway." (PMID 22654667, 2012).
lung cancer (continued). "In this case, we used KRAS gene mutation analysis to support that the lung carcinoma represented a metastatic pancreatic carcinoma as they both possessed identical codon 12 KRAS mutations." (PMID 23119210, 2012). "Somatic KRAS mutations have been associated with resistance to EGFR-targeted agents in lung cancer and metastatic CRC, and are mutually exclusive with EGFR mutations in large series of NSCLC." (PMID 21943394, 2011). "KRAS is mutated in 10%–30% of lung carcinomas and over 95% of all activating mutations in KRAS are located in exon 1 (codons 12 and 13)." (PMID 21408138, 2011). "In lung cancer cell lines knockdown of KRAS using siRNA demonstrates that the RAS pathway signature is a better measure of dependence on RAS compared to KRAS mutation status." (PMID 20591134, 2010). "Mutations in KRAS have been found in 20% to 30% of lung cancers and are believed to play a key role in this malignancy." (PMID 21124782, 2010). "Taken together, when the phenotype of LKB1 mutation is examined in the setting of known alterations of lung cancer, an interesting association of KRAS dependence appears, with specific clinical and treatment potential." (PMID 18728656, 2008). "Constitutively active KRAS mutations are highly prevalent in lung cancers, but the direct role of its downstream phosphatidylinositol 3-kinase (PI3K) pathway in tumor progression remains unclear." (PMID 41676515, 2026). "In lung cancer cells with KRAS mutations, the expression level of NOX4 is markedly elevated." (PMID 41328353, 2026). "Among other commonly detected mutations in lung cancer patients, KRAS mutations were identified in approximately 4.5 % of cases, while EML4-ALK fusions were detected in only 0.5 % of patients, suggesting potential limitations of ctDNA profiling in detecting fusions." (PMID 40503459, 2025). "Combining these KRAS G12C inhibitors and irradiation could enhance efficacy in KRAS G12C mutated lung cancer." (PMID 40361506, 2025). "Further subtypes of patients with KRAS mutation‐ positive lung cancer are necessary." (PMID 40337291, 2025). "We reported that the interplay between KRAS (Kirsten rat sarcoma viral oncogene homolog) and menin plays an important role in regulating the development of lung cancer and that the loss of menin leads to neuroendocrine (NE) differentiation in KRAS mutant-induced lung adenocarcinoma." (PMID 40057469, 2025). "KRAS stands out as one of the most prevalent mutated genes in lung cancer." (PMID 40568576, 2025). "However, the present study included only 4 observations with both CPS values and KRAS mutations, all from lung cancer cases." (PMID 41515496, 2025). "Somatic mutations may be associated with environmental exposures, such as KRAS in lung cancer with smoking." (PMID 41162424, 2025). "Although DPP4 has been implicated in other malignancies, its specific role in KRAS-mutant lung cancer and association with ICI resistance remain unknown." (PMID 41283988, 2025). "Therefore, this systematic review and meta-analysis aim to clarify the value of radiomics in predicting KRAS mutation status in lung cancer." (PMID 41584578, 2025). "The KRAS oncogene is one of the most commonly altered genes in human solid tumors, with activating mutations detected in up to 80% of pancreatic cancers and a substantial proportion of colorectal and lung cancers." (PMID 41375035, 2025). "In lung cancer, mutation of KRAS codon 12 can be characterised by a G:C > T:A base substitution." (PMID 40970185, 2025).
lung cancer (continued). "The KRAS isoform most commonly causes pancreatic, colonic, biliary tract, and lung cancers." (PMID 40943615, 2025). "In addition, lung cancer samples with KRAS mutations showed higher mRNA levels of MT-CO2, c-JUN, or GLS1." (PMID 39747079, 2025). "The aim of our study is to evaluate whether different KRAS mutation subtypes may play a role in modulating the response to immunotherapies in lung cancer." (PMID 41463229, 2025). "Indeed, DEK overexpression in vitro was associated with an increase in EGFR, KRAS, and vimentin levels in lung cancer cell lines and poor prognosis according to patient database analyses." (PMID 39852534, 2025). "This phenomenon has been observed in pancreas, colon and lung cancers harbouring KRAS mutations." (PMID 39820726, 2025). "The transformation of KRAS from a proto-oncogene to an active oncogene explains why KRAS mutations are implicated in various types of cancer, including pancreatic, colorectal, and lung cancers." (PMID 41098412, 2025). "For instance, loss of CMTR2 promotes proliferation of KRAS-driven lung cancer cells." (PMID 41198678, 2025). "Given that KRASG12C mutation is the most prevalent KRAS mutation in lung cancer, we investigated whether RASON regulates KRASG12C activity and its oncogenic functions in NSCLC." (PMID 40128846, 2025). "Combined cisplatin with metformin, combined inhibition of SRC, PI3K, and MEK1/2, HSP90 inhibition, FAK inhibition, hexosamine biosynthesis pathway inhibition, and a mitochondrial inhibitor phenformin have been found effective in KRAS/LKB1 co-mutated lung cancer models." (PMID 40611261, 2025). "However, further research is required to elucidate its role as a biomarker for ICIs in KRAS-mutant lung cancer and its relationship with other co-mutations associated with ICI resistance." (PMID 41283988, 2025). "Oncogenic KRAS mutations are present in approximately 30% of non–small cell lung cancers (NSCLCs)." (PMID 41086023, 2025). "KRAS mutations are the most common mutations in lung cancers (25–37% in lung adenocarcinoma)." (PMID 40361506, 2025). "Given that both DDB2 and XPC are key components of NER machinery, we sought to determine whether the NER pathway is involved in KRAS mutation–driven platinum resistance in lung cancer." (PMID 39960727, 2025). "However, management and treatment options for pediatric lung cancer patients harboring KRAS mutations remain limited." (PMID 40296044, 2025). "Constitutively active mutations of KRAS are prevalent in non–small cell lung cancer (NSCLC)." (PMID 39960727, 2025). "Additionally, KRAS mutations are associated with poor prognosis in lung cancer with bone metastases, highlighting their importance in guiding therapeutic decisions." (PMID 40342734, 2025). "The objective of this study was to investigate the correlation between circulating tumor DNA (ctDNA) KRAS G12C–mutation dynamic variations and treatment outcomes in patients with advanced non‐small cell lung cancer (NSCLC) receiving sotorasib therapy in a real‐world setting." (PMID 40445863, 2025). "Notably, KRAS mutations are detected in approximately 90% of pancreatic cancers, 50% of colorectal cancers, and 30% of lung cancers." (PMID 40128846, 2025). "The presence of KRAS mutations in resected lung cancer is associated with a poor prognosis." (PMID 39744567, 2025). "KRAS-mutant lung cancers are distinguished by recurrent loss of the tumor suppressor STK11/LKB1." (PMID 40316540, 2025). "KRAS mutation is an important factor that promotes the progression of lung cancer." (PMID 40691458, 2025). "Besides, KRAS mutation, frequently associated with smokers, has also been linked to PD-L1 expression in lung cancer." (PMID 40612952, 2025).